AHR (aryl hydrocarbon receptor)
Diseases named in the same sentence as AHR in open-access papers (continued):
Sharing a sentence is not in itself a finding about the gene and the disease.
tumor (continued). "A similar mechanism in the tumor microenvironment induced CD8+ T cell exhaustion via IL-2-mediated STAT5 activation and tryptophan hydroxylase-1 expression, leading to AhR activation." (PMID 39211042, 2024). "As a result, the activation of AhR in different tumors demonstrated a consistent promotion of MMPs, which therefore affect EMT and the further tumor progression." (PMID 38434684, 2024). "The conversion of Trp to indoles metabolized by lactic acid bacteria increases TAM AhR activity, recruiting TNF-α+IFN-γ+CD8+ T cells in PDAC, exerting an anti-tumor immune effect." (PMID 38462620, 2024). "This alteration activated the intestinal AHR and GPCRs signaling pathways while inhibiting STAT3 phosphorylation, which subsequently suppressed tumor cell proliferation and angiogenesis." (PMID 39710789, 2024). "Released aryl hydrocarbon receptor (AhR) agonist indole-3-aldehyde (I3A) and CD8 T cells within the tumor microenvironment." (PMID 39351241, 2024). "Constitutive expression of TDO in tumor cells can be regulated similarly to that of IDO1, involving signaling via the COX-2/PGE2 and AhR pathways, while other TDO-regulating pathways have been described as well." (PMID 39211039, 2024). "have demonstrated that the endogenous ligand of AhR, derived from TDO, Kyn, can down-regulate the anti-tumor effects and enhance the survival rate of tumor cells through the AhR pathway." (PMID 38680494, 2024). "Correspondingly, high AHR expression in PDAC patients correlates with poor clinical outcomes and features of immunosuppressive TAMs, supporting the tumor-promoting role of AHR in PDAC." (PMID 38612627, 2024). "Microbiome-derived formate increases cancer stemness while inducing AhR signaling, which accelerates CRC tumor expansion." (PMID 39351241, 2024). "Activation of AhR by KYN, a product of IDO1 and TDO2, prompts the generation of immune-tolerant dendritic cells (DCs) and regulatory T cells, which together shape a tumor immune microenvironment incapable of recognizing and destroying cancer cells." (PMID 38887298, 2024). "Upon exposure to IFN-γ and IFN-β, tumor-regenerating cells exhibit elevated expression of indoleamine 2,3-dioxygenase (IDO) and aromatic hydrocarbon receptor (AHR)." (PMID 38795254, 2024). "In this review, we highlight AhR signaling pathways in the TME and their contributions to tumor survival and invasion." (PMID 38434684, 2024). "The small molecule AHR inhibitor IK-175 increases pro-inflammatory macrophages and activates CD8+ T cells in tumour-draining lymph nodes." (PMID 38831013, 2024). "The AhR inhibitor HP163, developed by Hercules Pharmaceuticals, reduced tumor growth in oral, breast, and skin orthotopic tumor models, and was shown to decrease immunosuppressive CD11b+ cells in the draining lymph nodes of oral squamous cell cancer." (PMID 38339226, 2024). "In glioblastoma, kyn activates AhR in TAM to regulate its function and T-cell immunity, correlating with poor tumor prognosis." (PMID 38434684, 2024). "T cells can regulate Tumor repopulating cells (TRC) that can induce CD8+ T cells to express PD-1 through Kyn uptake and AhR activation through IDO-Kyn-AhR pathway." (PMID 38415258, 2024). "ITE reduces proliferation, migration, and in vivo tumor growth of AN3-CA, HCE-1B, and Ishikawa cells in an AhR-dependent manner." (PMID 38807762, 2024). "AHR is an endogenous KYN receptor that is thought to be important in immunomodulation and tumour development." (PMID 38935536, 2024). "High expression of AhR and its target genes, CYP1A1 and CYP1A2, has been correlated with increased histological grade, tumor stage, and progression in muscle-invasive bladder cancer and upper urinary tract cancers." (PMID 38807762, 2024).
tumor (continued). "Inhibition of AhR increases STING levels and reduces tumor growth under cisplatin or STING agonist treatment." (PMID 37670034, 2023). "mRNA levels of HIF-1α, AhR, and of their target genes as well as of ARNT and nuclear receptor coactivator NCOA2 were determined in tumor tissues from patients in whom the tumor was promptly removed either with or without prior endovascular embolization." (PMID 37305351, 2023). "Tumor cells produce IDO to turn tryptophan into kynurenine, which interacts with aryl hydrocarbon receptor in the TME, thereby leading to tryptophan depletion and facilitating Treg production." (PMID 36816749, 2023). "TDO2 in turn activated the Kyn–AhR pathway, which enhanced glycolysis, which stimulates the anabolic growth of cancer cells and CXCL5 secretion to recruit macrophages to the tumor microenvironment." (PMID 37232717, 2023). "ERCC6L, AHR and KIF2C downregulation were found to be potential mechanism of anti-tumor property of esketamine." (PMID 37968758, 2023). "In a study of Merkel cell carcinoma (MCC), MCC cells with lower IDO1 expression but a tumour microenvironment with lower TDO2 and AhR expression had a longer overall survival rate." (PMID 38062922, 2023). "Given the role of ROS in AHR regulating PYGL, we pretreated tumor-bearing mice with antioxidants including NAC or GEE before drug treatment." (PMID 38099490, 2023). "The researchers observed that AHR activation significantly upregulated the expression of kisspeptin 1 (KISS1), a molecule known to inhibit tumor metastasis." (PMID 37943609, 2023). "For example, GBM cell–derived kynurenine would activate the aryl hydrocarbon receptor (AHR) in TAMs, which, in turn, upregulates CCR2, thus promoting TAM infiltration and tumor growth." (PMID 36594466, 2023). "Then PD-1 in the nucleus of the T-cells is upregulated by the activation of AHR within CD8+ T-cells, thereby promoting tumor evasion of immune monitoring and tumor progression." (PMID 36925967, 2023). "Multiple Trp metabolites can activate AHR, and TDO2/IDO-mediated Trp metabolites can mediate other progrowth pathways in tumor cells." (PMID 37607000, 2023). "On the other hand, Kyn, as an endogenous aryl hydrocarbon receptor (AhR) agonist, contributes to immunosuppression of the TME and supports tumor immune escape." (PMID 37924140, 2023). "The butyrate induction of the melatonergic pathway has the potential to be problematic, under conditions of AhR activation that increases the NAS/melatonin ratio, giving the potential for released NAS to have trophic effects on tumor cells via TrkB activation." (PMID 37970210, 2023). "It was identified that epacadostat potently activates AhR-mediated signaling, inducing the nuclear translocation of AhR and the upregulation of IDO1 expression in both tumor cells and splenic T cells, leading to immunosuppression." (PMID 37122718, 2023). "Lymphoma growth was promoted in AHR−/− mice, whereas treatment with the AHR ligand 6-formylindolo[3,2-b]carbazole (FICZ) inhibited tumor growth." (PMID 37394584, 2023). "Inhibition of AHR with the antagonist CH-223191 suppresses CCL2-induced TAM infiltration and tumor growth." (PMID 36594466, 2023). "There was a significant retrogression of the tumors generated from AhR-silenced-MOC1 cells by week 2 and sustained inhibition of tumor growth was reported over a time span of 7 weeks." (PMID 37830596, 2023). "The ability of AhR to sequester ARNT, as the obligate heterodimer partner of the pro-angiogenic factor HIF-1α, has been proposed as a tumor-suppressive mechanism conferred by the expression of AhR." (PMID 37106727, 2023).
tumor (continued). "AhR knockdown in ER-negative, MDA-MB-231 cells decreased proliferation and wound healing but induced apoptosis and inhibited tumor growth in an athymic nude mouse xenograft model." (PMID 36428667, 2022). "Particularly, TRP depletion and KYN generation, through aryl hydrocarbon receptor (AhR), induce suppression of effector T cells and generation of T regulatory cells (Treg) by FOXP3 induction in the tumor microenvironment." (PMID 35408802, 2022). "In Tamoxifen-resistant MCF7 cells, AhR antagonism inhibited the BCSC population and also inhibited tumor growth." (PMID 36588678, 2022). "The association between Malassezia-produced indoles and BCC is considered to be the result of AhR mediated local metabolic and immune aberrations, while ICZ (like TCDD) are considered tumor inducer substances." (PMID 35458697, 2022). "Studies have demonstrated that AHR signalling maintains normal ISC proliferation by promoting Znrf3 and Rnf43 expression to suppress aberrant WNT-β-catenin signalling and tumour progression." (PMID 36555220, 2022). "Meanwhile, the accumulation of kynurenine promotes aryl hydrocarbon receptor (AHR) nuclear translocation, which can accelerate tumor escape from immune surveillance by triggering the generation of immunosuppressive cells." (PMID 35571116, 2022). "As indicated, a powerful aspect of NK cell control by the tumor is via IDO induction, thereby converting tryptophan to kynurenine, which activates the AhR." (PMID 36613754, 2022). "Although recent studies show that tryptophan-derived microbial metabolites suppress anti-tumor immunity by activating AhR in tumor-associated macrophages, data are lacking to determine whether tryptophan-derived metabolites are implicated in H pylori-induced reduction of cancer immunotherapies." (PMID 35677057, 2022). "The AHR binds to kynurenine produced by IDO, promoting immunosuppression by increasing Treg development, which inhibits anti-tumor immune response." (PMID 36072596, 2022). "For example, a study demonstrated that IFN-γ induced tumor-repopulating cells (TRCs) to enter dormancy to evade immunotherapy, which was mediated by an indolamine 2,3-dioxygenase 1 (IDO1)-kynurenine (Kyn)-aryl hydrocarbon receptor (AhR)-p27 dependent pathway." (PMID 35177584, 2022). "In fact, AhR activation by microbiome-produced tryptophan catabolites promotes the suppressor functions of PDAC TAMs, which reduces tumor infiltration of CD8+ T cells." (PMID 36713558, 2022). "As transporters including SLC7A5 also transport Kyn, they can contribute further to its influx into tumours, thereby bypassing IDO, TDO and FAMID, activating the AhR, further enhancing IDO expression, and undermining invading T-cell function." (PMID 36286592, 2022). "Transcription factor aryl hydrocarbon receptor (AHR) has emerged as one of the main regulators involved both in different homeostatic cell functions and tumor progression." (PMID 35465323, 2022). "Recent preclinical research on the AhR receptor (which is activated by immunosuppressive metabolites of tryptophan produced by IDO1) demonstrated that AhR blockade can reverse TME immunosuppression and synergise with ICB to reduce tumour growth." (PMID 34944851, 2021). "Top upregulated master regulators in the tumor, as compared to the parent cells, include ZEB2 and PHLDA1; while top downregulated master regulators include AR, AHR, and ITGA6." (PMID 33808801, 2021). "To fill this gap, we attempted to investigate the IHC expression of AhR, N-cadherin, E-cadherin and CD147, considering the correlation found in various cancer types between their expression and tumour aggressive behaviour." (PMID 34640369, 2021). "During inflammation of the microenvironment and tumor progression, KYN is pronounced in adequate amounts to activate AhR in humans." (PMID 34202246, 2021).
tumor (continued). "Harnessing the Trp-indole pathways in bacteria and the host hold the potential to attack the tumor cells through several different facets; Trp starvation, IDO1 inhibition, and indolic AhR activation." (PMID 33916690, 2021). "Usually, at the early stages of tumour progression, the production of immunosuppressive factors by tumours is poor, allowing high levels of IFN secreted by the CTLs or NK cells for IDO1/AhR activation." (PMID 34539663, 2021). "IPA was reported to exert its effects by activating AHR and PXR, and higher expression of AHR and PXR was inversely related to cancer cell proliferation and the stage and grade of the tumor." (PMID 34966278, 2021). "Through stimulation of the aryl hydrocarbon receptor (AhR), the IDO/TDO/Kynurenine pathway promotes immune tolerance in the tumor microenvironment via suppression of NK cells and cytotoxic T cells and promotion of regulatory T cells." (PMID 33766099, 2021). "Nonetheless, in neuroblastoma Kyn via AhR activation lead to KISS1 gene overexpression and in this mechanism it was shown to decrease tumor metastasis and improve patient overall survival." (PMID 34071442, 2021). "ROS levels in breast cancer cells are associated with the expression and activity of the transcription factor AHR, which controls tumor growth and chemokine production in the TME, and regulating the TME can influence tumor progression." (PMID 34660577, 2021). "It has been shown that tumor/exosomal IDO produces kynurenine by degrading tryptophan, which in turn can induce IDO activity in DCs by interacting with the aryl hydrocarbon receptor (AHR)." (PMID 34078376, 2021). "To test this, we utilized RNA expression levels of AHR and SULT1C2 generated by the TCGA PanCancer study through the Tumor-Immune Estimation Resource (TIMER2.0) portal." (PMID 35010676, 2021). "Compared to the parent LNCaP cells, expression of AR, AHR, CDH1, CXCR7, FLNA, ITGA6, and UGT2B15 in tumor was significantly inhibited." (PMID 33808801, 2021). "Metabolites such as the tryptophan metabolite-kynurenine (produced by tumor cells and TAMs) has been found to suppress CD8 Teff cells via aryl hydrocarbon receptor (AHR) signaling and consequently upregulation of PD-1." (PMID 34200820, 2021). "Polydatin inhibited the protein expressions of AHR, CYP1A1, and HSP-90, which are tumor grade-related markers, and the IC50 concentration of polydatin was 20 μM." (PMID 34577602, 2021). "However, the mechanism by which modulation of AHR can inhibit tumor metastasis remains unknown." (PMID 32546278, 2020). "Nevertheless, it has to be considered that the implementation of AhR as a therapeutic target might be very complex and many factors, such as type of ligand and its pharmacokinetics, cell type and cell environment (inflammation, tumor) should be taken into account." (PMID 32899152, 2020). "In this study, we show that the AhR-active proton pump inhibitor omeprazole (OME) acts as a selective AhR modulator (SAhRM) and decreases growth and invasion of GBM cells in culture and inhibits tumor growth in vivo." (PMID 32731514, 2020). "The capacity of CSCs to increase kynurenine release and AhR activation to the NK cell release of IFNγ may be important to the initiation and development of immune suppression in the tumour microenvironment, especially as NK cells are often the first cytolytic cell to encounter tumours." (PMID 33375613, 2020). "Again, the authors showed that IFN-γ treatment resulted in IDO1/AhR-dependent p27 induction, that prevented STAT1 signaling, suppressing cell death and inducing tumor cell-dormancy in murine TRCs." (PMID 32296435, 2020).
tumor (continued). "Kynurenine activation of the AhR induces COX2-PGE2 and EP4 receptor activation in NK cells, leading to the suppressed/‘exhausted’ NK phenotype that is typical in the tumour microenvironment, and which is paralleled in severe SARS-CoV-2 infection." (PMID 32867244, 2020). "This would indicate that O-GlcNAcylated YY1 will interact with AhR activation to increase the NAS/melatonin ratio, and thereby NAS trophic support for tumours." (PMID 33375613, 2020). "Interestingly, we could counteract canonical AhR activity with specific antagonists, such as the natural flavonoid resveratrol to decrease the pool of BRAFi resistant/persister cells, and thus delay tumor relapse." (PMID 32708687, 2020). "Lower AHR and PXR expression correlate with higher disease stage, grade, and enhanced mitotic activity in the tumor." (PMID 33050543, 2020). "As such, an initial increased release of pro-inflammatory cytokines, especially IFNγ, from NK cells in the tumour microenvironment drives IDO induction in cancer cells, leading to intracrine kynurenine activation of the AhR that acts to protect cancer cells." (PMID 33375613, 2020). "As such, the co-ordinated suppression of melatonin production and raised TGF-β allows AhR activation to heighten TGF-β levels and effects across the various cells of the tumour microenvironment." (PMID 33375613, 2020). "Histopathology imaging features of anatomic structures show that higher expression of STAT3, AHR, and CCR2 modules distinguishes between samples derived from the cellular tumor compared with those from leading edge and infiltrating tumor regions." (PMID 32383980, 2020). "KYNs binding to AhR have been shown to alter the proliferation and function of several immune effectors, including CD8+ T cells, and provide tumor cells with a means to elude anticancer immunosurveillance." (PMID 32957545, 2020). "So, the net result of an AhR-induced BRCA1 inhibition is the stimulation of aromatase and E2 (estradiol) increase in tumor cells, which sustains cell proliferation." (PMID 32722276, 2020). "Taken together, our data suggest that an engagement of the AHR pathway by IDO or TDO-derived Kyn can drive a Treg-macrophage suppressive axis and tumor progression." (PMID 32782249, 2020). "Altogether, our results indicate that the engagement of both AhR and GPR30 functions, in particular in an ER-negative/triple-negative context of breast cells, favors tumor progression and leads to poor prognosis." (PMID 32670863, 2020). "The authors demonstrated that AhR–AREG signaling pathway induced tumorigenesis by controlling ROS and promoting the tumorigenic functions of the tumor microenvironment." (PMID 33015128, 2020). "Based on our previous study and in vitro data presented here, activation of AhR by OME suppressed proliferation of the GBM cells, reducing tumor mass and slowing tumor growth." (PMID 32731514, 2020). "Hypothetically, the IFN-γ-STAT1 signaling induces apoptosis in proliferating tumor cells; however, TRCs-induced overexpression of IDO1 and AhR, shifts IFN-γ action and give rise to IDO1/AhR-induced p27 activation and inhibition of STAT1 signaling." (PMID 31430951, 2019). "TDO was found to be constitutively expressed in glioblastomas and excessive production of the AHR agonist KYN was found to contribute to the immune escape, higher motility and survival of tumor cells." (PMID 31781097, 2019). "Blocking the AHR led to decreased TAM infiltration and tumor growth with concomitant increased survival of the animals." (PMID 31547627, 2019). "However, whether these AhR agonists exhibit tumor-initiating activity remains unclear." (PMID 30872677, 2019). "Kyn represents a major endogenous ligand in the activation of immunoregulatory AhR, yet activated AhR can modulate IDO1 expression in DCs and tumor cells." (PMID 31481962, 2019).